TAF11L2 (TATA-box binding protein associated factor 11 like 2)
Tractability: No criterion of Open Targets' tractability assessment is met for any kind of drug.
Gene: Protein-coding gene on chromosome 5 (17,498,231 to 17,498,827, forward strand). Ensembl gene ENSG00000284373.
Gene Ontology:
Molecular function: RNA polymerase II general transcription initiation factor activity; protein heterodimerization activity
Biological process: RNA polymerase II preinitiation complex assembly; transcription initiation at RNA polymerase II promoter
Cellular component: transcription factor TFIID complex; nucleus
Homologues: Orthologues: tropical clawed frog taf11 (48% identical), zebrafish taf11 (46% identical), Drosophila melanogaster Taf11 (44% identical), Caenorhabditis elegans taf-11.1 (36% identical), Caenorhabditis elegans taf-11.2 (30% identical). Paralogues in human: TAF11L13 (93% identical), LINC02218 (92% identical), TAF11L10 (92% identical), TAF11L12 (92% identical), TAF11L5 (92% identical), TAF11L6 (92% identical), TAF11L7 (92% identical), TAF11L8 (92% identical), TAF11L3 (91% identical), TAF11L4 (91% identical), TAF11L9 (91% identical), TAF11L11 (89% identical), and 2 more.